MUC2 (mucin 2, oligomeric mucus/gel-forming)
Diseases named in the same sentence as MUC2 in open-access papers (continued):
Sharing a sentence is not in itself a finding about the gene and the disease.
infection (continued). "Thus, we found significant interactions of diet and infection for several genes, especially those related to the mucosal barrier, such as DCLK1, HDAC9, IL13RA1, MUC2 and HDAC1 (Fold change 2.5, 1.9, 1.3, 1.3 and − 1.2, respectively)." (PMID 38081984, 2023). "Meanwhile, dietary EOA treatment also upregulated CLDN-1, OCLN, ZO-1, MUC2 and FABP2 mRNA levels at the middle infection phase, as well as linearly reduced the gene expression level of TLR4, NF-κB and IL-1β at the early infection stage in infected broiler chickens." (PMID 37391807, 2023). "In summary, the HLA, MUC2 and FUT2 loci show strong candidacy for a role in sputum production, with overlap with infection and related phenotypes and known mechanistic interactions between the genes at the FUT2 and MUC2 loci, suggesting that these signals are likely to be robust." (PMID 37263751, 2023). "Mucins such as Muc2 and Muc13 also were detected in all selected tissues in our study, further suggesting that SVCV invasion may lead to secondary infection." (PMID 33897703, 2021). "It was surprising that infection status did not have a significant effect on MUC2 mRNA levels at 7 or 10 d PI because other studies have found reduced MUC2 expression in the intestine during Eimeria infection." (PMID 33652244, 2021). "Therefore, the relative transcription of MUC2 and TFF3 was measured in colonic tissue samples taken at day 6 following peroral infection of secondary abiotic IL-10−/− mice." (PMID 34183045, 2021). "PAS and Muc2 staining of Itgb2mut mice revealed that there was no infection-induced hyperplasia in the mutant mice and no increase in Muc2 levels at D19 p.i. compared with WT." (PMID 33407124, 2021). "Likewise, we observed anti-correlated transcription of miR-615-3p with MUC2 and TFF3 mRNA upon established C. jejuni 81-176 infection in vivo." (PMID 34183045, 2021). "For MUC2 at 7 d PI, there was not a significant impact of either infection or feed and mRNA levels in test groups were only slightly lower than 100%." (PMID 33652244, 2021). "We observed fewer Muc2 positive cells in the colon of the Itgb2mut mice p.i. compared with WT (j **p < 0.01) suggesting that Itgb2mut mice did not have an infection-induced increase in the goblet cells and Muc2 secretion." (PMID 33407124, 2021). "To retain the loosely adherent layers of MUC2, we did not remove the media or wash colonoid monolayers before infection with EAEC strains." (PMID 32601325, 2020). "The expression of MUC2, a protective and antimicrobial mucoprotein, was also significantly decreased in the H9N2 infection group at 5 dpi and 12 dpi, while the mRNA expression level of MUC2 in the baicalin plus H9N2 AIV infection group was significantly upregulated (P < 0.01)." (PMID 33294434, 2020). "In fact, we did not observe the mucus layer penetration advantage conferred by Pic in absence of a MUC2 barrier as evidenced by infection of colonoids in which MUC2 expression was knocked down." (PMID 32601325, 2020). "C. rodentium infection in mice lacking Muc2 results in high mortality, whereas wild type (WT) mice clear the infection spontaneously, and clearance is delayed in mice with defective mucus exocytosis." (PMID 30665337, 2019). "To study this, we used antibiotics treated and non-treated specific pathogen free Muc2-/- and Muc2+/+ littermates and germ-free mice inoculated with Eh in colonic loops as a short infection model." (PMID 30500860, 2018). "L. intracellularis infection is associated with a decrease in mucus secreting goblet cells in the small intestinal epithelium marked by absence of glycoprotein MUC2 expression at the peak of infection." (PMID 30140680, 2018). "Our data indicate that the MUC expression by RSV and hMPV differs significantly, as we observed a stronger induction of MUC8, MUC15, MUC20, MUC21, and MUC22 by RSV infection while the expression of MUC1, MUC2, and MUC5B was dominated by the infection with hMPV." (PMID 25977598, 2015).
infection (continued). "Collectively, our data suggest that infections of mice with E. papillata not only induce pathogenesis in the jejunum, the final target site of E. papillata, but also induced an upregulation of TLR4 and a downregulation of MUC2." (PMID 24367242, 2013). "A high-dose T muris infection established in both WT and Muc2-KO mice showed no marked difference in the number of worms at day 13 after infection." (PMID 20138044, 2010). "Although there was little evidence of mature, glycosylated Muc2 in the KO mice, interestingly, on day 21 after infection, there was a faint band consistent with the electrophoretic migration of Muc2 in these mice." (PMID 20138044, 2010). "Additionally, PAstV–4 infection triggered the activation of the extracellular regulated protein kinases/ myosin light-chain kinase (ERK/MLCK) pathway, followed by the down-regulation of tight–junction proteins (occludin and ZO–1) as well as MUC–2 expression." (PMID 38891045, 2024). "However, the same study did not identify changes in MUC2 mRNA levels after infection with a simian RVA strain." (PMID 37848925, 2023). "The A. galli group (AG) after 7 days infection showed in jejunal segments the highest MUC2 production compared to non-infected and infected chickens given Zn (Zn and AG + Zn groups) without significance, as well to controls (C group) with statistical difference on the level p < 0.05." (PMID 36676016, 2022). "Therefore, we assume that the observed dysregulation of MUC2 and TFF3 upon in vitro and in vivo C. jejuni infection was associated to the stage of infection rather than to the strains." (PMID 34183045, 2021). "In the caecum, the SE infection did not affect the expression of Muc2 at 7 and 21 dpi." (PMID 34944274, 2021). "Furthermore, we investigated the effects of C. butyricum on the muc2 expression in IECs in vitro, and our data showed that after 2 and 6 h post-infection, the gene expression level of muc2 was not significantly different among the different groups (P > 0.05)." (PMID 32180765, 2020). "Similarly to the mucus changes during different time points of infection in WT animals, Muc1, Muc2, Muc4 or Muc6 mRNA levels did not explain the differences in mucus thickness between IFN-γ−/- and WT mice." (PMID 30665337, 2019). "In the absence of infection, IFN-γR-/- and wt control mice displayed no signs of mucosal pathology, equivalent numbers of mucus filled goblet cells and equivalent mRNA levels for muc2, the gene encoding the key secreted goblet cell mucin (p≥0.05; 0 dpi)." (PMID 21829463, 2011). "However, in WT but not Ifnar1-/- mice, PR8 infection enhanced cecal Muc2 levels." (PMID 27149619, 2016). "However, upon infection with this attenuated strain of S. typhimurium, no major changes were evident in histological parameters in the colon, in mucus composition, or in the level of the secretory protein mucin 2 (E left graph MUC2), the primary component of the protective mucous layer in the colon." (PMID 37020718, 2023). "Moreover, MUC2 and MUC5AC not just as a structural component of the mucus barrier but also act as a crucial effector molecule during infections of the intestine." (PMID 25365201, 2014).
cancer (140 papers, 2005 to 2026). A tumor composed of atypical neoplastic, often pleomorphic cells that invade other tissues. "Loss of MUC2 alters the composition of the microbiota, which ultimately results in inflammation or cancer." (PMID 39727412, 2025). "MUC2 has been reported to be associated with cancer metastatic processes, and ELAVL1 was identified as a central oncogenic driver for malignant growth and metastasis of peripheral nerve sheath tumor." (PMID 39593114, 2024). "IPA showed significant changes in the expression levels of genes associated with gastrointestinal disease (Abcb1, Guca2a, Muc2, Rag2, Itga6, and Shh), inflammatory disease (Abcb1, Muc2, and Rag2), and cancer (Muc2, Guca2a, and Rag2)." (PMID 33396408, 2020). "Hath1 over-expression was shown to induce the expression of both MUC2 colonic mucins mRNAs and the cell cyle regulator P27Kip1 in association with a decreased survival/proliferation of cancer cells." (PMID 23409082, 2013). "In the univariate analysis, MUC1 and MSLN expression were associated with aggressive cancer biology (i.e. short survival group) and MUC2 expression was associated with favorable biology (i.e. long survival group)." (PMID 22792233, 2012). "Aberrant expression of the membrane-bound form of mucin, MUC1, and the secreted form of mucin, MUC2, may be associated with cancer growth, differentiation, transformation, and invasion." (PMID 37337182, 2023). "Interestingly, although MUC5AC positive cancers are associated with significantly worse overall survival in patients, MUC2 cancers show a much more indolent phenotype." (PMID 34475526, 2022). "They compared histological specimens from the initial resection with specimens from the repeat resection by means of pyrosequencing assay for Kirsten rat sarcoma (KRAS) mutations and immunohistochemistry for mucin (MUC) 1 and MUC2 to distinguish between cancer recurrence and new primary lesion." (PMID 28716115, 2017). "In the context of this condition, we concluded that COX-2+ cancer cells could be a critical co-factor in the poor prognosis caused by MUC2 overexpression in addition to MUC2-induced COX-2+ and M2 TAMs." (PMID 24324582, 2013). "This is the first report in which minisatellites of the complete MUC2 region have been characterized in detail, and our observations suggest that MUC2 minisatellite loci may function as indicators of cancer risk." (PMID 18000536, 2007). "Notably, both increased and decreased expression of MUC2 are associated with cancer progression." (PMID 39061654, 2024). "Additionally, we suggest that minisatellite instability might be associated with MUC2 function in cancer cells." (PMID 18000536, 2007). "MUC2 downregulation leads to the activation of STAT3 and Chk2, suppression of CREB phosphorylation, and loss of E-cadherin, facilitating cancer progression and metastasis." (PMID 41378310, 2025). "MUC2 is primarily expressed in gel-forming goblet cells and has been suggested as a potential biomarker for identifying the intestinal subtype of AoV cancer." (PMID 38893239, 2024). "On the other hand, another secreted mucin, MUC2, is considered intestinal mucin and is rarely expressed in normal gastric mucosa but is reexpressed in the intestinal metaplasia or pre-cancer lesion." (PMID 39886661, 2024). "To identify genes specific to PBMCs in the cell fractions, we compared DEGs between CTRL cancer cells + PBMCs and MUC2 K.O. cancer cells + PBMCs." (PMID 39926604, 2024). "Specifically, the removal of MUC2 in HT-29 cells resulted in heightened immune infiltration and enhanced allogenic recognition of cancer cells." (PMID 39926604, 2024). "Total of 17 cells in cluster 6 were further defined as cancer cells with Paneth cell properties (Paneth+) or goblet cell properties (Goblet+) using the relevant marker genes expression, Lyz1, Muc2, and Atoh1." (PMID 39535280, 2024). "We then intersected this list with DEGs from comparing CTRL cancer cells alone to MUC2 K.O. cells alone in 3D culture." (PMID 39926604, 2024).
cancer (continued). "At the same time, the expression patterns of mucins, including MUC1 and MUC2, were found to be different from those of the surrounding concomitant cancer tissues." (PMID 37337182, 2023). "The MUC family genes were specifically highly expressed in cancer and epithelial cells, and MUC2 was the most highly expressed MUC family gene, especially in MC cancer cells and some epithelial cells." (PMID 36690709, 2023). "For NECE, five genes were mutated in 80% of patients, including PIK3CA, FAT3, MUC2, PLEC, and TTN, among which PIK3CA and FAT3 belong to the COSMIC Cancer Gene Census gene tier 1 and 2, respectively." (PMID 37920164, 2023). "Muc4 maintains the intestinal homeostasis by upregulation of Muc2 and Fam3D (guardians of the gut) and downregulation of cancer-promoting mucin (Muc13)." (PMID 35255004, 2022). "Its high abundance in cancer is probably associated with changes in mucins expression associated with CRC progression, including an upregulation of MUC5AC and downregulation of MUC2, and even the loss of its expression in some patients." (PMID 34209683, 2021). "With structural similarity to von Willebrand factor (vWF), MUC2 can also bind to collagen or other connective tissue components, making cancer cells lose permeability to resist chemotherapy." (PMID 34300195, 2021). "We interrogated if a similar mechanism was present in other carcinomas-muc and found that the expression of MUC2 was regulated by DNA methylation in CRC-muc, BRCA-muc and STAD-muc." (PMID 33947930, 2021). "Additional rationale for the use of these drugs include the basal over-expression of COX-2 and FASN in MCC and prior studies demonstrating inhibition of MUC2 expression/secretion by targeting these two cancer pathways." (PMID 32811515, 2020). "It is accepted that MUC2 is expressed in normal colon epithelial cells, but abnormal levels of MUC2 can be found in various malignant tumors and precancerous lesions." (PMID 32695780, 2020). "Suggestive of an anteriorization of epithelial identity is the fact that these cancers often express gastric epithelial markers, including mucin 2 (MUC2), MUC5AC, MUC6 and annexin A10 (ANXA10)." (PMID 31739541, 2019). "MUC1, MUC2, MUC4, and MUC16 are mucins associated with cancer progression, whereas MUC16 is also used for cancer diagnostics." (PMID 31552050, 2019). "This chemoresistance has been partially attributed to the protective barrier formed by the extracellular MUC2 protein surrounding the cancer cells." (PMID 29290997, 2017). "Though MUC2 has been shown to be the predominant mucin family member in these cancers, the upstream signaling initiators of MUC2 expression in these malignancies are poorly understood." (PMID 28640835, 2017). "MUC2 mutations increase with the increasing disease stage in KIRP, appearing in 9.5% of stage I KIRP (n = 95) and up to 50% of stage IV KIRP cancers (n = 10)." (PMID 28978023, 2017). "Loss of MUC2 and strong expression of IL-6 and CD68 were also detected in serial sections of one specimen from another patient with stage IIA cancer (lower left and lower right)." (PMID 28725043, 2017). "We systematically analyzed MUC2 and IL-6 expression and determined the survival of cancer patients with high or low MUC2 and IL-6 expression using the Oncomine and PrognoScan databases, respectively." (PMID 28725043, 2017). "Our experiments showed that IL-6 treatment induced STAT3 and Chk2 activation and attenuated CREB/ATF-1 phosphorylation in MUC2-silenced HT-29 cancer cells." (PMID 28725043, 2017). "We found that MUC2 staining was positive in 4 of 11 samples, including 3 signet ring carcinomas and 1 well-differentiated adenocarcinoma." (PMID 27277677, 2016). "In our study, a high level of MUC2 expression in cancer cells was found to be correlated with a significantly increased level of COX-2 expression in TAMs and accompanied by a greatly elevated level of PGE2 in the local tissue." (PMID 24324582, 2013).
cancer (continued). "To establish the relationship between the expression status of MUC2 in cancer tissue and COX-2 expression level in TAMs we compared the densities of COX-2+ TAMs in cancer specimens between the high and low MUC2 expression groups." (PMID 24324582, 2013). "The densities of CD68+ cells in the cancer tissues from the high MUC2 expression group and the low MUC2 expression group were similar (27.3±13.6 mm-2 vs. 26.0±11.9 mm-2); and no statistical significance was established (p=0.654, Student’s t test)." (PMID 24324582, 2013). "When MUC2 gene expression was inhibited, HIPEC was demonstrated experimentally to have increased effectiveness, and the protection of MUC2 covering the surface of cancer cells decreased." (PMID 22266876, 2012). "In addition, LRI-201 treatment also reversed the increment of MUC2 mRNA expression induced by LIF suggesting a potential role of the axis LIF/LIFR/FGFR4 in the onset of cancer." (PMID 37945798, 2024). "In summary, our flow cytometry analysis revealed that the knockout of MUC2 in HT-29 cells resulted in the increased proliferation of E/A PBMCs and in immune cell infiltration in the cancer cell spheroids, leading to increased cancer cell death and reduction in cancer spheroids." (PMID 39926604, 2024). "MUC2 expression in intestinal metaplasia in the neighborhood of the carcinomas may play an important role in GC." (PMID 39886661, 2024). "CAMKV and MUC2 are the most enriched genes in areas of carcinoma (SSES = 1.37 and SSES = 1.29 respectively), whilst NCR1 (synonym: CD335) and CLEC6A, both selectively expressed in Natural Killer cells (NK-cells), are spatially localised to lymph nodes (SSES = 8.59 and SSES = 6.42 respectively)." (PMID 39003292, 2024). "Poorly differentiated (G3) carcinomas tended to show a loss of CDX2 (27/33 cases) but not of MUC2 and MUC5AC." (PMID 37240039, 2023). "Paradoxically, MUC2 has increased expression level in certain types of gastrointestinal malignancies, which denotes that MUC2 may also be employed by cancer cells and function as a mucous barrier against antitumour immune reaction." (PMID 35910854, 2022). "Our study also suggested that the existence of MUC2 predicts a worse survival rate in PDAC, which may be the clinical evidence that cancer cells exploit MUC2 to form a protective mucous barrier to evade from immune attack." (PMID 35910854, 2022). "Fusobacterium nucleatum, as a cancer-promoting biological factor, can be enriched to the lesion through the specific interaction of Fap2 with Gal-GalNAc antigen on the tumor surface, and lead to the expression of MUC2 and TNF-α in cancer cells." (PMID 36081564, 2022). "MUC2 is commonly used as a biomarker for many cancers as well as other diseases." (PMID 36612133, 2022). "Clinical studies assessed the role of MUC2 as a potential therapeutic immune target in cancers." (PMID 36612133, 2022). "It is suggested that MUC2 overexpression in cancer may reflect the mucin forming nature of the cancer’s cells rather than the intrinsic action of mucin." (PMID 33808549, 2021). "Nevertheless, our results suggest that up-regulation of MUC2 and the gel-forming mucins signature might be considered as pan-cancer biomarkers of mucinous histology." (PMID 33947930, 2021). "RT-PCR analysis of β-catGOF; Mll1−/− organoids confirmed a decreased expression of Gata4 and revealed a concomitant upregulation of Bmp4 and the secretory differentiation markers Mmp7 and Muc2, identifying Mll1 as an upstream regulator of Gata4/Bmp4-controlled cancer stemness and differentiation." (PMID 33349639, 2020). "In MUC2-/- mice, bacteria reached crypts that are normally covered by mucin and were in direct contact with the epithelial cells and induced inflammation and cancer in these mice." (PMID 33333934, 2020). "However, in CRC cells, a glycosylation defect of the MUC2 gene in cancer cells leads to a failure to express the normal mucus type." (PMID 32695780, 2020).